HTRA1 (HtrA serine peptidase 1)
Description:
Serine protease with a variety of targets, including extracellular matrix proteins such as fibronectin. HTRA1-generated fibronectin fragments further induce synovial cells to up-regulate MMP1 and MMP3 production. May also degrade proteoglycans, such as aggrecan, decorin and fibromodulin. Through cleavage of proteoglycans, may release soluble FGF-glycosaminoglycan complexes that promote the range and intensity of FGF signals in the extracellular space. Regulates the availability of insulin-like growth factors (IGFs) by cleaving IGF-binding proteins. Inhibits signaling mediated by TGF-beta family members. This activity requires the integrity of the catalytic site, although it is unclear whether TGF-beta proteins are themselves degraded. By acting on TGF-beta signaling, may regulate many physiological processes, including retinal angiogenesis and neuronal survival and maturation during development. Intracellularly, degrades TSC2, leading to the activation of TSC2 downstream targets.
Synonyms: HTRA; PRSS11; IGFBP5-protease; ARMD7; CADASIL2; CARASIL; CARASIL2; L56; ORF480
Tractability: Small molecule: a high-quality ligand is known; it has a high-quality binding pocket. Antibody: UniProt places it where antibodies can reach, with high confidence; its Gene Ontology location is reachable by antibodies, with high confidence; UniProt predicts a signal peptide or a membrane-spanning region; the Human Protein Atlas places it where antibodies can reach. PROTAC: ubiquitination databases record sites on it; its protein half-life has been measured; a small molecule that binds it is known.
Target class: Enzyme; Hydrolase
Gene: Protein-coding gene on chromosome 10 (122,458,551 to 122,514,907, forward strand). Ensembl gene ENSG00000166033.
Subcellular location: Cell membrane; Secreted; Cytoplasm, cytosol
Subcellular location (Human Protein Atlas): Plasma membrane; Predicted to be secreted
Pathways (Reactome):
Extracellular matrix organization: Degradation of the extracellular matrix
Gene Ontology:
Molecular function: identical protein binding; molecular function activator activity; protein binding; serine-type endopeptidase activity; serine-type peptidase activity
Biological process: positive regulation of apoptotic process; programmed cell death; proteolysis
Cellular component: extracellular exosome; extracellular matrix; extracellular region; plasma membrane; cytosol
Genetic constraint (gnomAD): Loss-of-function variants: 19 observed, 31.93 expected, observed/expected ratio (o/e) 0.6, 90% interval 0.41 to 0.87. The upper end of that interval is the gene's LOEUF score, 0.87, which puts it in group 3 of 6, group 1 being the genes least tolerant of losing a copy. Missense variants: 511 observed, 555.7 expected, observed/expected ratio (o/e) 0.92, 90% interval 0.85 to 0.99. Synonymous variants: 267 observed, 231.01 expected, observed/expected ratio (o/e) 1.16, 90% interval 1.04 to 1.28.
Homologues: Orthologues: chimpanzee HTRA1 (99% identical), macaque HTRA1 (99% identical), dog HTRA1 (95% identical), mouse Htra1 (92% identical), rat Htra1 (92% identical), pig HTRA1 (89% identical), zebrafish htra1b (71% identical), zebrafish htra1a (69% identical), guinea pig HTRA1 (66% identical), rabbit HTRA1 (65% identical), tropical clawed frog htra1 (65% identical). Paralogues in human: HTRA3 (56% identical), HTRA4 (51% identical), HTRA2 (39% identical).
Diseases named in the same sentence as HTRA1 in open-access papers:
HTRA1 is named in the same sentence as 231 diseases in open-access papers, as found by Europe PMC text mining. Sharing a sentence is not in itself a finding about the gene and the disease. The quoted sentences say what the papers report.
age-related macular degeneration (71 papers, 2007 to 2025). Age-related loss of vision in the central portion of the retina (macula), secondary to retinal degeneration. "Polymorphisms in the ARMS2/HTRA1 locus on chromosome 10 enhance the risk of geographic atrophy and macular neovascularization, the advanced forms of age-related macular degeneration (AMD)." (PMID 40832922, 2025). "Among more than 100 associated loci, the most prominent are complement factor H (CFH) and age-related maculopathy susceptibility 2/high temperature requirement A serine peptidase 1 (ARMS2/HTRA1)." (PMID 41516080, 2025). "We leveraged the CKP carboxypeptidase A1 inhibitor as a scaffold to construct phage-displayed CKP libraries and subsequently screened these collections against HTRA1, a trimeric serine protease implicated in age-related macular degeneration and osteoarthritis." (PMID 38777835, 2024). "HtrA1 is homotrimeric serine protease, which has been implicated in diseases, such as Alzheimer’s disease, osteoarthritis, cancer and age-related macular degeneration." (PMID 38547109, 2024). "HTRA1 is a trypsin fold serine protease implicated in various diseases, including Alzheimer’s disease, cancer, arthritis and age-related macular degeneration." (PMID 39556614, 2024). "Genetic studies have revealed complement factor H on chromosome 1 and age-related maculopathy susceptibility 2 and high-temperature requirement A serine peptidase 1 (ARMS2/HTRA1) genes on chromosome 10 as candidate genes associated with the risk for nAMD." (PMID 39091492, 2024). "Inflammation and elevated expression of high temperature requirement A serine peptidase 1 (HTRA1) are known high risk factors for age-related macular degeneration (AMD)." (PMID 36903482, 2023). "The trimeric serine protease HTRA1 is a genetic risk factor associated with geographic atrophy (GA), a currently untreatable form of age-related macular degeneration." (PMID 36064790, 2022). "Two major loci were commonly identified in GWAS studies – the complement factor H locus (CFH) and the ARMS2/HTRA1 (Age-related maculopathy susceptibility 2/High temperature requirement A1) locus." (PMID 36064790, 2022). "HtrA1 has been implicated in a diverse range of pathological conditions, including cancer, age-related macular degeneration (AMD) and preeclampsia." (PMID 34639128, 2021). "Polymorphisms in the promoter region of HTRA1 are strongly associated with age-related macular degeneration (AMD)." (PMID 34563186, 2021). "HtrA1 is implicated in a wide range of human diseases such as arthritis, age-related macular degeneration, cancer, and preeclampsia." (PMID 29768431, 2018). "Among these, HtrA1 is implicated in several cancers, cerebrovascular disease and age-related macular degeneration." (PMID 29093542, 2017). "Mutations in HTRA1 are associated with the development of age-related macular degeneration and small vessel disease, and recently HTRA1 has been shown to colocalise with tangles and plaques in AD brain." (PMID 28386764, 2017). "The ARMS2/HTRA1 genes at the 10q26 locus have been associated with risk of age-related macular degeneration (AMD), with the most significantly associated variants being A69S (rs10490924), del443ins54 (EU427539) and rs11200638." (PMID 23592919, 2013). "Polymorphisms in the HTRA1 gene lesion: Distribution and Allele in neovascular Age-Related Macular Degeneration (nAMD), Polypoidal Choroidal Vasculopathy, and Controls in the northern Chinese Population." (PMID 23326481, 2013). "Polymorphisms in the HTRA1 gene lesion: Distribution and Genotypes in neovascular Age-Related Macular Degeneration (nAMD), Polypoidal Choroidal Vasculopathy, and Controls in the northern Chinese Population." (PMID 23326481, 2013). "Age related macular degeneration (AMD): HTRA1 SNPs versus ARMS2 single nucleotide polymorphisms (SNPs)." (PMID 21031019, 2010).
age-related macular degeneration (continued). "HTRA1, one of four human family members, is a primarily secreted protein originally linked to tumorigenesis and arthritis and subsequently implicated in other conditions including age-related macular degeneration (AMD)." (PMID 39081996, 2023). "A putative transcription factor binding site of the HTRA1 gene in the 10q26 region was shown to confer significant risk for choroidal neovascularization in age related macular degeneration (AMD) and SNPs rs1061170, rs3753394 in CFH and rs10490924 in ARMS2/LOC387715 showed significant association." (PMID 21067572, 2010). "High-temperature requirement A1 (HtrA1) has been identified as a disease-susceptibility gene for age-related macular degeneration (AMD) including polypoidal choroidal neovasculopathy (PCV)." (PMID 36142120, 2022). "Genome-wide association studies have identified genetic variation at the ARMS2/HTRA1 locus as a risk factor for the development and progression of age-related macular degeneration (AMD)." (PMID 32345717, 2020). "CFH and HTRA1 genes are traditional markers of increased risk of age-related macular degeneration (AMD) across populations." (PMID 30257524, 2018). "It lies next to the ARMS2/HTRA1 genes in a region of chromosome 10q26, where single nucleotide variants have been strongly associated with age-related macular degeneration (AMD), the commonest cause of blindness in Western populations." (PMID 27416785, 2016). "A single nucleotide polymorphism (SNP), rsll200638, was identified in the HtrA1 gene promoter and found to be significantly correlated with age-related macular degeneration (AMD) with a population-attributable risk of 49.3%." (PMID 22935172, 2012). "Single nucleotide polymorphisms (SNPs) in the tightly linked LOC387715/ARMS2 and HTRA1 genes have been associated with age-related macular degeneration (AMD)." (PMID 19065273, 2008). "Variants in complement factor H (CFH), the hypothetical LOC387715, and the high-temperature requirement A-1 (HTRA1) genes have been reported to be associated with age-related macular degeneration (AMD)." (PMID 18682812, 2008). "A therapeutic monoclonal antibody created to treat age-related macular degeneration renders HTRA1 inactive by locking the loop A and R227 in separate positions." (PMID 41190437, 2025). "HTRA1 and oxidative stress act synergistically to promote macrophage infiltration and inflammation in age-related macular degeneration (AMD)." (PMID 36547458, 2022). "We found two different loci in AbdAge (rs932274, p = 1E−10) and Pancreas Accelerated Age (rs2672597, p = 3.9E−9) respectively that are close to genes implicated in age-related macular degeneration (PLEKHA1, ARMS2, HTRA1)." (PMID 35418184, 2022). "HTRA1, a protein shown to be involved in the pathophysiology of age-related macular degeneration, has been shown to induce an accumulation of lipofuscin and melanolipofuscin between the photoreceptor and retinal pigment epithelial layers when overexpressed." (PMID 33809186, 2021). "HtrA1 is involved in the pathophysiological mechanisms of these diseases, such as osteoarthritis, dementia, and age-related macular degeneration." (PMID 33743591, 2021). "In addition, HTRA1-mediated proteolysis has been implicated in carcinogenesis 19, age-related macular degeneration (AMD) 20 and familial ischemic cerebral small-vessel disease." (PMID 33746601, 2021). "The two most common genetic contributors to age-related macular degeneration (AMD), a leading cause of irreversible vision loss worldwide, are variants associated with CFH-CFHR5 on chromosome 1 (Chr1) and ARMS2/HTRA1 on chromosome 10 (Chr10)." (PMID 33273512, 2020). "HtrA1 is a serine protease suggested to play a role in the pathogenesis of various diseases, including age-related macular degeneration and osteoarthritis, by modulating extracellular matrix or cell surface proteins." (PMID 29695130, 2018).
age-related macular degeneration (continued). "As a result of the interaction with MPPs, the proteolytic activity of HtrA1 against Fibulin-5, a specific HtrA1 substrate in age-related macular degeneration (AMD), was increased." (PMID 25506911, 2014). "The purpose of this study was to investigate the association of ARMS2/HTRA1 and CFH SNPs with early age-related maculopathy (ARM) in a Han Chinese cohort." (PMID 23687431, 2013). "This locus includes the age-related maculopathy susceptibility (ARMS2) gene and the gene encoding for the high-temperature requirement factor A of serine peptidase 1 (HTRA1)." (PMID 24369445, 2013). "Recent findings that variants in complement factor H, B, complement component 2 (C2), and LOC387715/HTRA1 genes may increase the risk to develop age-related macular degeneration (AMD) provide insight into the pathological process of AMD." (PMID 17615538, 2007). "We have published a review article on “elastin turnover in ocular diseases: A special focus on age-related macular degeneration”, that highlights the multitude of enzymes other than neutrophil elastase (elastase 2), cathepsin L and HTRA1 with elastase-like activity present in ocular tissues." (PMID 37174708, 2023). "A similar approach might also be useful in other conditions with HTRA1 involvement such as neurodegenerative diseases, age-related macular degeneration and TGFβ-induced protein (TGFBIp)-linked corneal dystrophies." (PMID 39081996, 2023). "HTRA1, a primarily secreted serine protease, degrades a number of substrates that involve in a variety of disease processes such as neurodegeneration, age-related macular degeneration, and arthritis." (PMID 36581876, 2022). "The aim of this study was to explore whether there are interactions between genetic (ARMS2/HTRA1) and environmental factors (cigarette smoking) in the pathogenesis of age-related macular degeneration (AMD)." (PMID 35138344, 2022). "Therefore, inhibition of HTRA1 activity could be of potential therapeutic benefit for several diseases, such as arthritis, osteoporosis, Schwannoma and age-related macular degeneration." (PMID 38777835, 2024). "In addition, it was reported that HTRA1 participate in the extracellular deposits of proteins and lipids on the basal side of retinal pigment epithelium, which contribute to the pathogenesis of age-related macular degeneration." (PMID 35461232, 2022). "What are the independent and combined associations of the 2 most common genetic risk loci for age-related macular degeneration (AMD)—chromosomes 1 (CFH-CFHR5) and 10 (ARMS2/HTRA1)—with disease progression?" (PMID 35113155, 2022). "HtrA1 is induced by oxidative stress and protects cells from oxidation-induced cell death at the expense of promoting cell senescence in retinal pigment epithelial cells, a mechanism that may link HtrA1 with the onset of age-related macular degeneration." (PMID 29768431, 2018). "In recent years, human high temperature requirement A1 (HtrA1) has been the subject of drug discovery efforts in age-related macular degeneration (AMD), owing to the prevalence of high-frequency HTRA1 variants in affected subjects." (PMID 28992183, 2017). "Single nucleotide polymorphisms (SNPs) of age-related maculopathy susceptibility protein 2/HtrA serine peptidase 1 (ARMS2/HTRA1) and complement factor H (CFH) have been reported to be associated with age-related macular degeneration (AMD)." (PMID 23687431, 2013). "Serine protease (HTRA1) and age-related macular degeneration susceptibility factor 2 (ARMS2) are both found in retinal tissues, and their serum expression is significantly elevated in AMD patients." (PMID 40365539, 2025). "The high-temperature requirement A1 (HTRA1), a serine protease, has been demonstrated to play a pivotal role in the extracellular matrix (ECM) and has been reported to be associated with the pathogenesis of age-related macular degeneration (AMD)." (PMID 39927462, 2025).
age-related macular degeneration (continued). "The interaction between HTRA1 and the TGF-β family has been verified in various diseases, including brain development, age-related macular degeneration and tumours." (PMID 34946854, 2021).
CARASIL (64 papers, 2010 to 2025). CARASIL is a hereditary cerebral small vessel disease characterized by early-onset gait disturbances, premature scalp alopecia, ischemic stroke, acute mid to lower back pain and progressive cognitive disturbances leading to severe dementia. "The loss of HTRA1 function has been reported to cause cerebral autosomal recessive arteriopathy with subcortical infarcts and leukoencephalopathy (CARASIL), an inherited form of cerebral SVD characterized by an early-onset stroke in young adults." (PMID 36581876, 2022). "Cerebral autosomal recessive arteriopathy with subcortical infarcts and leukoencephalopathy (CARASIL) is a genetic disorder characterized by mutations in the HTRA1 gene." (PMID 35163523, 2022). "Loss-of-function mutations in the high-temperature requirement A serine peptidase 1 (HTRA1) gene cause cerebral autosomal recessive arteriopathy with subcortical infarcts and leukoencephalopathy (CARASIL)." (PMID 31316458, 2019). "Homozygous loss-of-function mutations of human HTRA1 cause a hereditary cerebral small vessel disease (SVD) called cerebral autosomal recessive arteriopathy with subcortical infarcts and leukoencephalopathy (CARASIL)." (PMID 29768431, 2018). "Cerebral autosomal recessive arteriopathy with subcortical infarcts and leukoencephalopathy (CARASIL) is a hereditary disease caused by loss-of-function mutations in the Htra1 gene, characterized by baldness, strokes, white matter lesions, and early-onset dementia." (PMID 38765773, 2024). "Cerebral autosomal recessive arteriopathy with subcortical infarcts and leukoencephalopathy (CARASIL) is an inherited cerebral small vessel disease (CSVD) caused by biallelic mutations in the high-temperature requirement serine peptidase A1 (HTRA1) gene." (PMID 37009886, 2023). "Cerebral autosomal recessive arteriopathy with subcortical infarcts and leukoencephalopathy (CARASIL) is a hereditary cerebral small vascular disease caused by a homozygous mutation in the high-temperature requirement A serine peptidase 1 (HTRA1) gene." (PMID 35222251, 2022). "CARASIL (cerebral autosomal recessive arteriopathy with subcortical infarcts and leukoencephalopathy) (OMIM 600142) causes lacunar stroke and early onset vascular dementia, and derives from recessive mutations in the HtrA serine protease (HTRA1) gene, which is involved in TGF-beta signaling." (PMID 27393281, 2016). "Cerebral autosomal recessive arteriopathy with subcortical infarcts and leukoencephalopathy (CARASIL) is associated with the HtrA serine peptidase 1 (HTRA1) gene mutation, which encodes a serine protease." (PMID 40699631, 2025). "Similar to CADASIL, cerebral autosomal recessive arteriopathy with subcortical infarcts and leukoencephalopathy (CARASIL) is a genetic form of vascular dementia, caused by mutations in the HTRA1 gene." (PMID 39881338, 2025). "CSVD related to HTRA1 mutations includes both cerebral autosomal recessive arteriopathy with subcortical infarcts and leukoencephalopathy (CARASIL), caused by biallelic HTRA1 variants, and heterozygous HTRA1-related CSVD2." (PMID 40634305, 2025). "The Htra1–/– mice have also been used to study cerebral autosomal-recessive arteriopathy with subcortical infarcts and leukoencephalopathy (CARASIL) pathogenesis where loss of HTRA1 causes increased vascular smooth muscle cells in the thoracic aorta." (PMID 39927462, 2025). "HTRA1 is implicated in another CSVD known as CARASIL, where mutations in the Htra1 gene cause dysfunctional HTRA1, which leads to cerebral small vessel pathology, WM damage and VCID48–50." (PMID 38600214, 2024). "In contrast to previously documented cases, we initially report an exceptional individual with a heterozygous mutation of HTRA1 who exhibited nearly all the classic features of CARASIL along with severe clinical manifestations and rapid progression." (PMID 37799144, 2023).